TRPV6 (transient receptor potential cation channel subfamily V member 6)
Diseases named in the same sentence as TRPV6 in open-access papers (continued):
Sharing a sentence is not in itself a finding about the gene and the disease.
pancreatitis (8 papers, 2020 to 2025). Inflammation of the pancreas. "Recent studies that have reported an association of TRPV6 mutations with chronic pancreatitis in multinational, multiethnic cohorts strengthen a causative link between mutant TRPV6 and pancreatitis." (PMID 36699452, 2022). "TRPV6 mutations have very recently been identified in pancreatitis patients of Japanese, Chinese, and European ethnicity, but there have been no reports from the South Asian population." (PMID 36699452, 2022). "Upregulation of the TRPV6 wild-type allele in heterozygous carriers by vitamin D administration has been reported earlier and could provide a promising therapeutic approach for pancreatitis research in the future (Sahin-Tóth, 2020)." (PMID 36699452, 2022). "This combined effect of mutations in TRPV6 and CASR would lead to intra-ductal Ca2+ overload, an established causal factor for premature activation of pancreatic enzymes and pancreatitis." (PMID 36699452, 2022). "We therefore monitored transcript levels of TRPV6 in the mouse pancreas following onset of acute pancreatitis in a well-established model of cerulein-induced pancreatitis." (PMID 36699452, 2022). "Recently, the p.N34S mutation was found in 20% of patients carrying the functionally defective TRPV6 variants, suggesting that the combination of mutated TRPV6 and SPINK1 p.N34S results in predisposition to pancreatitis, as well as the CFTR gene." (PMID 33375361, 2020). "Additionally, studies have reported that TRPV6 can regulate calcium ion balance and pancreatic inflammation in pancreatitis." (PMID 39742020, 2024). "Translating the observation that induction of pancreatitis in mice robustly induced TRPV6 expression, we propose that the aberrant activity of mutant TRPV6 may initiate pancreatitis and its severity due to increased expression during active disease." (PMID 36699452, 2022). "A recent publication shows that a small percentage of patients with nonalcohol dependent pancreatitis contain mutations that affect the TRPV6 gene." (PMID 34884497, 2021). "TRPV6 in pancreatic acinar cells might play a protective role against pancreatitis in mice." (PMID 41247519, 2025). "The patient did not have known pancreatitis-associated mutations, such as PRSS1, SPINK1, CTRC, CPA1, or TRPV6." (PMID 36419930, 2022).
chronic pancreatitis (5 papers, 2021 to 2025). A chronic inflammatory process causing damage and fibrosis of the pancreatic parenchyma. "Variants in the TRPV6 gene have also been associated with nephrolithiasis and chronic pancreatitis when inherited in an autosomal recessive manner." (PMID 37810884, 2023). "A subpopulation of patients with chronic pancreatitis shows mutations in one TRPV6 allele." (PMID 34884497, 2021). "Pancreas-specific Trpv6 knockout mice developed more severe acute and chronic pancreatitis than the control mice." (PMID 41247519, 2025).
hyperparathyroidism (5 papers, 2019 to 2026). Hyperfunction of the parathyroid glands resulting in the overproduction of parathyroid hormone. "Since the malfunction of the mutated TRPV6 protein changes Ca2+ homeostasis in the placenta and leads to hyperparathyroidism, we analysed whether the dysfunction of the channel alters the protein expression profile in the placenta of the affected child." (PMID 34884497, 2021).
Hypocalcemia (5 papers, 2021 to 2026). An abnormally decreased calcium concentration in the blood. "Chronic hypocalcemia promotes an inflammatory microenvironment by activating the TRPV6 calcium channel, which enhances the differentiation of Th17 cells and the secretion of IL-17A." (PMID 40766324, 2025). "Glucocorticoids have been shown to decrease intestinal calcium absorption by decreasing expression of TRPV6 and CalD9k and increased urinary excretion of calcium, but clinically significant hypocalcemia in healthy individuals is uncommon." (PMID 35011173, 2021). "Repression of Trpv6 and S100g might contribute to the more severe hypocalcemia and rickets phenotype observed in VdrΔAF2 mice." (PMID 39164247, 2024).
prostate adenocarcinoma (5 papers, 2009 to 2023). "We determined the frequencies of the two TRPV6 alleles within Caucasians and compared these frequencies with genotypes obtained from prostatic adenocarcinoma specimen." (PMID 19857260, 2009). "Therefore we compared the TRPV6 allele frequencies from Caucasian control individuals with the DNA obtained from prostatic adenocarcinoma tissue samples." (PMID 19857260, 2009). "On the other hand, ovarian cystadenocarcinoma (n = 585, r = 0.29, p < 0.001) and prostate adenocarcinoma (n = 494, r = 0.36, p < 0.001) showed statistically significant correlation between TRPV6 mRNA and TRPV6 gene copy number." (PMID 31897233, 2020). "Previous studies indicated that TRPV6 modulates proliferation of LNCaP human prostate adenocarcinoma or INS-1E cells via NFAT-dependent mechanisms." (PMID 27450545, 2016). "Several studies have shown that TRPV6 transcripts are expressed in locally advanced prostatic adenocarcinoma, metastatic and androgen-insensitive prostatic lesions but are undetectable in healthy prostate tissue and benign prostatic hyperplasia." (PMID 19857260, 2009). "TRPV6 is overexpressed in prostatic adenocarcinoma tissue and we next extracted genomic DNA from a total of 142 prostate tissue samples and analyzed the second polymorphism by the restriction enzyme Bsp1286I." (PMID 19857260, 2009). "In contrast TRPV6 is a highly Ca-selective cation channel and its transcripts are overexpressed in prostatic adenocarcinoma but undetectable in healthy and benign prostate tissue." (PMID 19857260, 2009). "We therefore asked if the TRPV6 genotype is correlated with prostatic adenocarcinoma and its progression." (PMID 19857260, 2009). "In prostate tissue the expression of TRPV6 is strictly correlated with the Gleason grading and the tumour staging implying that TRPV6 is an indicator for the metastatic potential of prostatic adenocarcinoma and a potential target for drugs which may be used to treat this disease." (PMID 19857260, 2009). "TRPV6 is absent in healthy prostates, and it becomes expressed in prostate adenocarcinoma where the TRPV6 mRNA level has been shown to correlate significantly with the Gleason grading and is abundantly expressed in lymph node metastasis of prostate origin." (PMID 36980711, 2023). "From the data we conclude that the TRPV6 genotype does not correlate with the progression of prostatic adenocarcinoma." (PMID 19857260, 2009). "TRPV6 transcripts are expressed in patients with advanced prostatic adenocarcinoma but are not detectable in healthy and benign prostate tissue." (PMID 19857260, 2009). "Furthermore the TRPV6 genotype is not correlated with the Gleason score and the tumour stage of prostatic adenocarcinoma samples." (PMID 19857260, 2009).
prostate tumor (5 papers, 2009 to 2025). "The immunohistochemistry analysis of prostate tumours demonstrated a very low expression level of CaSR and TRPV6 with a score between 0 and 1 (2E 2I and 2L)." (PMID 32931488, 2020). "By using quantitative MEMRI, this work has demonstrated the potential of manganese for different types of breast or prostate tumour animal models in presence of different CaSR or TRPV6 level expression." (PMID 32931488, 2020). "Similarly, activation of TRPV6 channels is strongly dependent on the cytosolic-free calcium concentration in prostate tumor cells." (PMID 40422222, 2025). "Therefore we asked whether TRPV6 allele frequencies of extraprostatic and intra-prostatic tumours (at time of resection) are different or not." (PMID 19857260, 2009).
benign prostatic hyperplasia (4 papers, 2009 to 2023). A non-cancerous nodular enlargement of the prostate gland. "Using in situ hybridization, TRPV6 could not be detected in benign prostatic tissue (including benign prostatic hyperplasia), prostatic intraepithelial neoplasia (high-grade PIN), or small, incidental adenocarcinoma." (PMID 37240443, 2023).
Hypercalcemia (4 papers, 2014 to 2025). An abnormally increased calcium concentration in the blood. "The association of 1,25D3 treatment with hypercalcemia is in part related to VDR-mediated expression of the epithelial Ca2+ channel TRPV6 (transient receptor potential vanilloid type 6)." (PMID 29030554, 2017). "These molecules have distinct chemical structures and are distinguished based on their hypercalcemia liability profile in a TRPV6 gene activation assay." (PMID 29030554, 2017). "Based on these data, Cmpd3 presented a VDRM selective activation profile of BGLAP over TRPV6 with significantly lower hypercalcemia liability (75.9 vs 17.4% Max." (PMID 29030554, 2017). "Although not fully understood, a possible hypothesis of hypercalcemia is an upregulation of epithelial calcium channels (TRPV6) in the intestine and kidney, and the active form of vitamin D (1,25-dihydroxyvitamin D3)." (PMID 40981014, 2025). "Specifically, systemic calcitriol levels can directly affect intestinal mineral absorption processes, e.g., by regulating SLC34A3 and TRPV6 expression, which are counterbalanced at the local level by calcitriol elimination to prevent hypercalcemia in L animals." (PMID 36005601, 2022). "However, supra-physiological levels of 1,25D3 activates the calcium-regulating gene TRPV6 leading to hypercalcemia." (PMID 29030554, 2017). "Whether the TRPV5 and TRPV6 overexpression in this context could directly contribute to tumourigenesis or represent a secondary event of hypercalcaemia needs to be further elucidated." (PMID 25164318, 2014). "Compounds were tested for their hypercalcemia liabilities in BGLAP and TRPV6 qPCR gene activation assays." (PMID 29030554, 2017).
kidney stone (4 papers, 2021 to 2023). "A mild gain of function ancestral variant of TRPV6 was associated with kidney stones, presumably because increased Ca2+ absorption in the intestines through TRPV6 was compensated by increased excretion of Ca2+ in the urine." (PMID 33853504, 2021). "The close homology and sequence similarity between TRPV6 and TRPV5 suggest that these approaches can also be extended to TRPV5-linked diseases, including hypercalciuria, nephrolithiasis, and bone disorders." (PMID 34725357, 2021).
cervical cancer (3 papers, 2021 to 2022). A primary or metastatic malignant neoplasm involving the cervix. "The expression of TRPV6 in cervical cancer is different from other cancers, and additional research will be needed to validate this difference, as well as to uncover the underlying mechanisms and develop novel therapeutic targets based on TRPV6." (PMID 36230965, 2022). "The expression of TRPV6 in early-stage cervical cancer was significantly correlated with the tumor stage, tumor growth type, tumor size, differentiation grade, and poor prognosis." (PMID 36230965, 2022). "Univariate and multivariate analyses identified TRPV6 as an independent prognostic factor for early cervical cancer patients’ survival, indicating that TRPV6 may be used as a novel prognostic marker for early cervical cancer." (PMID 36230965, 2022). "Moreover, the early-stage cervical cancer patients with a low TRPV6 expression had a short progress-free survival and overall survival duration." (PMID 36230965, 2022). "Trichostatin A suppresses cervical cancer cell proliferation and induces apoptosis and autophagy through regulation of the PRMT5/STC1/TRPV6/JNK axis." (PMID 34440894, 2021). "TSA suppresses cervical cancer cell proliferation and induces autophagic cell death through the regulation of the PRMT5/STC1/TRPV6/JNK axis." (PMID 34575981, 2021). "In cervical cancer cells, TSA (1 μM) induces autophagy by significantly suppressing protein arginine methyltransferase 5 (PRMT5) and transient receptor potential cation channel, subfamily V, member 6 (TRPV6) levels and enhancing stanniocalcin 1 (STC1) and JNK levels." (PMID 34575981, 2021).
Hypercalciuria (3 papers, 2013 to 2021). "Interestingly, NHERF4 is a known regulator of the Ca2+ channel TRPV6 that mediates the entry of dietary Ca2+ from the intestinal lumen into the enterocyte in the course of transepithelial transcellular Ca2+ absorption, which is nicely in line with the absorptive hypercalciuria we report." (PMID 26756164, 2016).
invasive breast carcinoma (3 papers, 2020 to 2022). A carcinoma that infiltrates the breast parenchyma. "MDA-MB-231 cells display relatively high TRPV6 levels in comparison to normal breast epithelial cells and non-invasive breast carcinoma cells, MCF7." (PMID 32895467, 2020). "To further understand the role of TRPV6 in mesenchymal cancer invasion, we utilized a commonly used, invasive breast carcinoma cell line, MDA-MB-231 for TRPV6-silencing." (PMID 32895467, 2020).
lymph node metastasis (3 papers, 2022 to 2023). "In a study of 96 prostatectomy specimens, TRPV6 mRNA transcript levels were positively correlated with Gleason/ISUP score, extraprostatic extension, and lymph node metastasis." (PMID 37240443, 2023). "We then examined the relationship between TRPV6 and the clinical characteristics of PDAC patients and found that a lower expression of TRPV6 is correlated with metastasis, advanced TNM stages of PDAC, and lymph node metastasis." (PMID 36012311, 2022). "Moreover, the patients with lymph node metastases (N1) had lower TRPV6 expression with a median RQ of 2.34 compared to patients without lymph node metastases (N0) with a median RQ of 0.54 (p = 0.0004)." (PMID 36012311, 2022).
osteoporosis (3 papers, 2020 to 2021). A condition of reduced bone mass, with decreased cortical thickness and a decrease in the number and size of the trabeculae of cancellous bone (but normal chemical composition), resulting in increased fracture incidence. "While Vitamin D and TRPV6 have been linked to various pathologies arising from calcium deployment, the most familiar effect is that of bone metabolism and in particular osteoporosis." (PMID 31897233, 2020). "TRPV6 is vital to Ca homeostasis and its defective expression or function is linked to transient neonatal hyperparathyroidism, Lowe syndrome/Dent disease, renal stone, osteoporosis and cancers." (PMID 34413465, 2021). "Taken together, our study suggests that Trpv6 is a potential therapeutic target for treating osteoporosis." (PMID 33159483, 2021). "It is interesting then that TRPV6 inhibitors can also reduce bone resorption in models of osteoporosis." (PMID 31897233, 2020). "Our in vivo studies revealed severe osteoporosis in Trpv6 knockout mice." (PMID 33159483, 2021). "We found that knockout of Trpv6 induced osteoporosis and enhanced bone resorption in mice, but did not affect bone formation." (PMID 33159483, 2021).
transient neonatal hyperparathyroidism (3 papers, 2020 to 2021). "Recently, mutations in the gene encoding transient receptor potential cation channel, subfamily V, member 6 (TRPV6) were identified as causative mutations of transient neonatal hyperparathyroidism (TNHP)." (PMID 32646367, 2020). "Previously, we found that mutations in TRPV6 cause transient neonatal hyperparathyroidism (TNHP) with bone abnormalities." (PMID 32646367, 2020). "Mutations in the gene encoding the TRP channel TRPV6 cause transient neonatal hyperparathyroidism (TNHP)." (PMID 32646367, 2020). "This is consistent with case reports in humans, where mutations in the Trpv6 gene lead to the hereditary human disease transient neonatal hyperparathyroidism (HRPTTN, OMIM #618188) associated with skeletal abnormalities, dysplasia, and elevated neonatal parathyroid hormone levels." (PMID 33352987, 2020). "Mutations in the gene encoding the transient receptor potential cation channel, subfamily V, member 6 (TRPV6) have been identified as causative mutations of transient neonatal hyperparathyroidism due to insufficient maternal–fetal Ca2+ transport in the placenta." (PMID 32646367, 2020).
asthenozoospermia (2 papers, 2022 to 2025). "Lin and Liang conclusively revealed by iTRAQ proteomics that the seminal EV proteome is altered in asthenozoospermia, notably showing a substantial decrease in TRPV6 levels in ASEVs and ejaculated sperm." (PMID 41465073, 2025).
breast tumor (2 papers, 2017 to 2024). "According to earlier research, breast tumor tissue expresses more TRPV6 mRNA and protein than normal breast tissue." (PMID 38534438, 2024). "The TRPV6 protein was discovered to be prevalent in the breast tumor tissue invading region by further investigations." (PMID 38534438, 2024).
deafness (2 papers, 2010 to 2019). An inherited or acquired condition characterized by the complete loss of the ability to hear from one or both ears. "It is perhaps more than a coincidence, therefore, that the genes for TRPV5 and TRPV6 are located on chromosome 7q35 and 7q33-34 respectively in human and the locus of the non-syndromic deafness gene DFNB13 is located at the encompassing region on chromosome 7q34-36." (PMID 20113508, 2010).
dermatitis (2 papers, 2021 to 2024). An inflammatory process affecting the skin. "TRPV6−/−knockout mice (TRPV6−/−) have been found to have substantial impairments in male fertility, increased urine Ca2+ excretion, reduced femur density, weight loss, dermatitis, and abnormalities in intestinal Ca2+ absorption." (PMID 38534438, 2024).
endotoxemia (2 papers, 2023). "The current study demonstrates that TRPV6 deficiency attenuates corticosterone-mediated promotion of alcohol-associated gut permeability, endotoxemia, and liver damage." (PMID 36817471, 2023). "First, TRPV6 deficiency attenuates corticosterone-induced intestinal mucosal permeability, TJ and AJ disruption, endotoxemia, systemic inflammation, and liver damage." (PMID 36817471, 2023). "A recent study has demonstrated that the transient receptor potential vanilloid 6 (TRPV6) channel plays a crucial role in alcohol-induced TJ breakdown, barrier impairment, endotoxemia, and increased inflammation." (PMID 36817471, 2023). "The absence of these effects of corticosterone on plasma LPS and cytokines in Trpv6-/- mice demonstrates that TRPV6 is involved in the mechanism of corticosterone-induced endotoxemia and systemic inflammation." (PMID 36817471, 2023). "A recent study indicated that the TRPV6 channel is essential in alcohol-induced intestinal epithelial TJ disruption, mucosal barrier impairment, endotoxemia, and liver injury." (PMID 36817471, 2023). "The genetic deletion of TRPV6 in mice prevented alcohol-induced intestinal barrier dysfunction, suggesting the mediatory role of TRPV6 in systemic inflammation and endotoxemia." (PMID 37887319, 2023). "TRPV6 is essential for alcohol-induced calcium influx in the intestinal mucosa, TJ breakdown, endotoxemia, systemic inflammation, and liver damage." (PMID 36817471, 2023). "Corticosterone and CRS disrupted TJ and AJ, increased intestinal mucosal permeability, and caused endotoxemia, systemic inflammation, and liver damage in wild-type but not Trpv6-/- mice." (PMID 36817471, 2023). "Therefore, we investigated the involvement of the TRPV6 channel in stress- and corticosterone-induced potentiation of intestinal permeability, endotoxemia, and systemic inflammation." (PMID 36817471, 2023). "Additionally, this study confirms the previous observation that CRS potentiates alcohol-induced gut permeability, endotoxemia, and liver injury and demonstrates that TRPV6 plays an essential role in the CRS-mediated promotion of alcohol effects in the gut and liver." (PMID 36817471, 2023). "Fourth, the lack of TRPV6 abrogates stress-mediated exacerbation of alcohol-induced gut mucosal permeability, endotoxemia, and liver damage." (PMID 36817471, 2023). "Second, the absence of TRPV6 blocks corticosterone-mediated enhancement of alcohol-induced gastrointestinal barrier dysfunction, endotoxemia, and liver injury." (PMID 36817471, 2023).